PLG (plasminogen)
Diseases named in the same sentence as PLG in open-access papers (continued):
Sharing a sentence is not in itself a finding about the gene and the disease.
Thromboembolism (4 papers, 2021 to 2024). The formation of a blood clot inside a blood vessel that subsequently travels through the blood stream from the site where it formed to another location in the body, generally leading to vascular occlusion at the distant site. "It is considered that elevated levels of vWF, FVIII, and fibrinogen, along with reduced fibrinolytic activity and decreased levels of plasminogen, contribute to the presence of a hypercoagulable state and a predisposition to thromboembolism and vascular diseases in patients with hyperthyroidis." (PMID 38541980, 2024). "In the treatment of thromboembolism, plasminogen activators, such as recombinant tissue-type plasminogen activators (rtPAs, or alteplase), remain the gold standard for acute thrombolytic therapy." (PMID 38794257, 2024). "Plasminogen activators, such as recombinant tissue-type plasminogen activators (rtPAs), while effective in treating thromboembolic diseases, often induce hemorrhagic complications due to non-specific enzyme activities in the systemic circulation." (PMID 38794257, 2024).
amyloidosis (3 papers, 2023 to 2025). A disorder characterized by the localized or diffuse accumulation of amyloid protein in various anatomic sites. "This is because amyloidosis is associated with many defects in platelet function and coagulation, including abnormal platelet aggregation, increased vascular fragility, factor IX and factor X deficiency, decreased alpha-2-plasmin inhibitor levels, and increased plasminogen levels." (PMID 38635103, 2024). "Plasminogen activation and plasmin activity appear to be involved in transthyretin amyloidosis including the initiation, progression, and tissue distribution of amyloid deposition." (PMID 37701910, 2023).
amyotrophic lateral sclerosis (3 papers, 2021 to 2022). Amyotrophic lateral sclerosis (ALS) is a neurodegenerative disease characterized by progressive muscular paralysis reflecting degeneration of motor neurons in the primary motor cortex, corticospinal tracts, brainstem and spinal cord. "Although the role of plasmin/plasminogen in the pathogenesis of amyotrophic lateral sclerosis remains to be elucidated, several studies have reported that plasminogen/plasmin is associated with the pathogenesis of amyotrophic lateral sclerosis." (PMID 36117913, 2022). "As one of those, our attention was initially on thrombin and plasminogen activators in synapse formation and elimination in the neuromuscular system, with orientation towards diseases such as amyotrophic lateral sclerosis (ALS) and how clotting and fibrinolytic pathways fit into its pathogenesis." (PMID 34827556, 2021).
Anxiety (3 papers, 2014 to 2025). Intense feelings of nervousness, tension, or panic often arise in response to interpersonal stresses. "The neuronal expression of plasminogen or tPA is involved in hippocampus-dependent learning or stress-induced response, including cognitive decline, depression- and anxiety-like behaviors." (PMID 24874880, 2014).
aspergillosis (3 papers, 2008 to 2024). Aspergillosis is an infection, growth, or allergic response caused by the Aspergillus fungus. "Plasminogen also appears to be a key regulator in susceptibility to aspergillosis." (PMID 36602962, 2023). "Additionally, increased susceptibility to aspergillosis has been observed in hematopoietic stem cell transplant patients with gene variants in TLR4, plasminogen, PFKFB3 polymorphisms, and other genetic factors." (PMID 39728022, 2024).
bladder cancer (3 papers, 2003 to 2024). "These hub nodes such as VEGFA, EGFR, ESR1, PLG, and MAPK3 were mainly enriched in pathways like proteoglycans in cancer, bladder cancer, and estrogen-signaling pathway." (PMID 32256653, 2020).
bladder tumour (3 papers, 2003 to 2024). "Finally, Ad5WS1 suppressed the growth of TCC-SUP bladder tumour xenografts, which could be augmented when combined with replication-defective adenoviral vector encoding kringles 1–5 of plasminogen (K1–5), an angiogenic inhibitor." (PMID 12778082, 2003). "Upon binding to its receptor uPAR, uPA activates plasminogen to plasmin, leading to the hydrolysis of the basement membrane and ECM, thereby impacting angiogenesis and cell migration, ultimately promoting the metastasis of bladder tumor." (PMID 39606239, 2024).
breast tumor (3 papers, 2009 to 2024). "For example, the growth of spontaneous breast tumors in polyoma virus middle T antigen (PyMT)‐expressing mice was unaffected by plasminogen deficiency." (PMID 37971174, 2024). "The aim of this study was to investigate the involvement of CK8 in plasminogen activation, and consequently in cell adhesion, invasion and signaling of breast tumor cells." (PMID 19845941, 2009). "These novel findings suggest a model in which CK8, together with uPA, plasminogen and fibronectin, constitutes a signaling platform capable of modulating cell adhesion/growth-dependent signal transduction in breast tumor cells." (PMID 19845941, 2009). "We have shown that anti-CK MAb, by diminishing the uPA mediated plasminogen activation in serum-free environment, affects the de-adhesion-invasion processes of breast tumor cells." (PMID 19845941, 2009).
Cerebral ischemia (3 papers, 2012 to 2018). Restriction of arterial blood supply to the brain associated with insufficient oxygenation to support the metabolic requirements of the tissue. "t-PA is an enzyme that works by catalyzing the conversion of plasminogen to plasmin which can then break down either the embolus or thrombus causing cerebral ischemia." (PMID 23335880, 2012).
fibrosis (3 papers, 2020 to 2023). the formation of excess fibrous connective tissue in an organ or tissue in a reparative or reactive process. "The effect of plasminogen on gene expression during the healing of radiation wounds was initially determined using the Mouse Wound Healing and Fibrosis RT2 profiler PCR arrays." (PMID 32205839, 2020).
fungal infections (3 papers, 2008 to 2022). "mAb 12D9 showed its ability to prevent host plasminogen being captured and “subverted” by C. albicans, providing a potential novel treatment strategy for invasive fungal infections." (PMID 33115324, 2020). "In summary, our study provides the evidence of C. albicans invading host by “subverting” plasminogen system, suggesting a potential novel treatment strategy for invasive fungal infections." (PMID 33115324, 2020). "We propose that genetic variation within the plasminogen pathway influences the pathogenesis of this invasive fungal infection." (PMID 18566672, 2008). "Besides, AfEno1 and C. albicans enolase (CaEno1) can bind to human plasminogen and then produce plasmin, subsequently improving the invasion and dissemination process during fungal infections." (PMID 35783432, 2022).
glaucoma (3 papers, 2017). Increased pressure in the eyeball due to obstruction of the outflow of aqueous humor. "Further, comparing the control and glaucoma samples the relative spectral counts of plasminogen peptides was significantly higher in the glaucoma (14 ± 0.5) compared to control samples (8 ± 1) (p < 0.01)." (PMID 28827627, 2017).
heart failure (3 papers, 2024 to 2025). Inability of the heart to pump blood at an adequate rate to meet tissue metabolic requirements. "Increased levels of plasminogen, heavy chain of plasminogen, furin, and prostasin have been found in the urine of rats with heart failure and adults with congestive heart failure." (PMID 38379911, 2024).
leukemia (3 papers, 2020 to 2024). A malignant (clonal) hematologic disorder, involving hematopoietic stem cells and characterized by the presence of primitive or atypical myeloid or lymphoid cells in the bone marrow and the blood. "In turn, conditioning of hepatocytes by a leukemic environment leads to the secretion of plasminogen, thereby, perpetuating this leukemia-propagating circuit." (PMID 39567540, 2024). "Next, we hypothesized, that leukemia cells influence the generation of plasminogen by hepatic cells, either directly or by conditioning of the BMM, which may secrete a mediator of hepatic plasminogen production." (PMID 39567540, 2024).
Lewis lung carcinoma (3 papers, 1982 to 2024). "Lewis lung carcinoma cells were implanted in the foot-pads of mice and the effects of the plasminogen-plasmin inhibitor tranexamic acid (t-AMCHA) and of the plasminogen activator urokinase on metastasis were examined by electron microscopy." (PMID 6751364, 1982).
liver disease (3 papers, 2021 to 2025). "Except for tPA and plasminogen activator inhibitor (PAI), all proteins involved in fibrinolysis are synthesized in the liver, and patients with liver diseases have lower plasma levels of plasminogen, α2-antiplasmin, factor XIII, and TAFI." (PMID 35518552, 2022). "Current understanding suggests that liver disease results in a state of rebalanced haemostasis due to alterations in both pro- and anti-haemostatic factors, including reduced levels of alpha-2 antiplasmin and plasminogen, as well as increased levels of tissue plasminogen activator (tPA) and PAI-1." (PMID 41001322, 2025).
liver fibrosis (3 papers, 2021 to 2025). "The role of PLG and HABP2 in liver fibrosis enhancement is acknowledged, while its cardiovascular effects remain uncertain." (PMID 38523778, 2024). "Besides, plasminogen activation and fibrinolysis biological process were also significantly enriched based on the 138 DEPs, these two biological processes may be also participate in the treatment process of hepatic fibrosis using PZH." (PMID 34417500, 2021).
lung adenocarcinoma (3 papers, 2020 to 2024). A carcinoma that arises from the lung and is characterized by the presence of malignant glandular epithelial cells. "One paper demonstrated that metastatic cells from breast and lung adenocarcinomas produce neuroserpin and serpin, inhibitors of plasminogen activators, to circumvent apoptosis by astrocytes when crossing the blood–brain-barrier." (PMID 34297239, 2022). "High expression of the plasminogen activation signature correlated with worse patient OS (p < 0.01) within the TCGA lung adenocarcinoma RNA-seq dataset and cohort." (PMID 32822576, 2020). "Moreover, the high expression of the plasminogen activation signature and SERPINE1 was associated with poor OS described within the TCGA lung adenocarcinoma RNA sequence dataset and clinical cohort." (PMID 38758826, 2024).
lung fibrosis (3 papers, 2020 to 2023). "The described mechanism can provide a rationale for the effect of plasminogen treatment on pulmonary fibrosis resolution being detected three weeks after its injection." (PMID 36674896, 2023). "There were ample evidence addressing the involvement of plasminogen activation in pulmonary fibrosis." (PMID 37964270, 2023). "Consistently, uPAR deficiency in mice contributed to more severe pulmonary fibrosis, weight loss and poor survival, which was resolved by plasminogen treatment that substantially decreased lung fibrosis in the absence of uPAR." (PMID 36674896, 2023). "Hence, the plasminogen treatment reverses lung fibrosis upon lung damage, which can serve as a promising therapeutic target for pulmonary fibrosis." (PMID 36674896, 2023). "This pathogenic effect can be resolved by plasminogen treatment, which substantially decreases lung fibrosis in the absence of uPAR." (PMID 36674896, 2023). "Therefore, bleomycin-induced lung fibrosis progressively resolved in plasminogen-treated mice." (PMID 36674896, 2023). "Finally, we found that mouse plasminogen intravenous administration (1 mg) could reverse lung fibrosis by reducing more than two-fold the fibrotic lung area in mice lacking uPAR expression (Plaur-/-) at day 42 after fibrosis induction." (PMID 36674896, 2023). "We hypothesized that the external introduction of plasminogen in the absence of uPAR might disrupt this vicious circle and reverse lung fibrosis." (PMID 36674896, 2023).
melasma (3 papers, 2018 to 2025). "Tranexamic acid (TA), an inhibitor of plasminogen activation, has been recently used in the treatment of melasma in different investigations." (PMID 30079087, 2018).
parasite infection (3 papers, 2017 to 2024). "Some studies indicate that patients with high parasitemia often experience alterations in coagulation tests, as high parasitemia is known to enhance fibrin formation and activate plasminogen, thus disturbing the coagulation system." (PMID 38698102, 2024). "Since activation of parasite-bound plasminogen is mediated by co-recruited mammalian tPA and uPA, plasminogen activation and parasite infection of both mosquito vector and mammalian host are inhibited in the presence of PAI-16." (PMID 35618711, 2022). "In conclusion, B. microti enolase is a multifunctional cytoplasmic protein which is also expressed at the parasitic outer surface, facilitates binding to host plasminogen, and could partially protect hosts against parasite infection." (PMID 28443086, 2017).
psoriasis (3 papers, 2011 to 2020). An autoimmune condition characterized by red, well-delineated plaques with silvery scales that are usually on the extensor surfaces and scalp. "In patients with psoriasis, we detected a diminished expression of PLG and increased production and activity of PL in PBMC or psoriatic lesions, thus confirming an enhanced PLG activity." (PMID 21311769, 2011). "Because cell-bound PLG is more efficiently activated to PL, we first examined the expression of PLG in PBMC from patients with psoriasis by flow cytometry." (PMID 21311769, 2011). "In summary, psoriasis patients have elevated levels of PLG activators which lead to a marked increase in the conversion of cell-bound PLG to the active PL." (PMID 21311769, 2011). "We found that plasminogen was diminished, but that the amount and activity of its converted product plasmin were markedly increased in psoriasis." (PMID 21311769, 2011). "PLG activators are highly elevated in the lesional skin of psoriasis patients, suggesting that PLG is involved in the pathogenesis of psoriasis." (PMID 21311769, 2011). "Collectively, our data implied that intact, cell-bound PLG was diminished in psoriasis, and this decrease may due to increased expression of its activators, uPA and tPA." (PMID 21311769, 2011). "Because increased levels of PLG activators were found in psoriatic lesions, we performed several experiments to examine whether PL, a major serine protease that can be converted from PLG by PLG activators, may be directly involved in pathogenesis of psoriasis." (PMID 21311769, 2011). "Although increased levels of plasminogen activators have been found in psoriatic lesions, the role of plasmin converted from plasminogen by plasminogen activators in pathogenesis of psoriasis has not been investigated." (PMID 21311769, 2011).
psychosis (3 papers, 2018 to 2021). "For data from the same subjects presently studied we previously reported that proteins involved in the plasminogen pathway, including MMP7 and Factor 7, predicted psychosis conversion." (PMID 29875399, 2018).
renal carcinoma (3 papers, 2012 to 2025). A carcinoma arising from the epithelium of the renal parenchyma or the renal pelvis. "Moreover, evidence has been provided that the anti-invasive properties of M6P/IGF2R in renal carcinoma cells are based on downregulation of cell-mediated plasminogen activation." (PMID 22521359, 2012). "To assess the importance of these 11 MMCGs, we employed Gene Dependency Scores (gDS) and found that BIRC5, PLG, and EIF4EBP1 had gDS scores below zero in most renal cancer cell lines." (PMID 40591061, 2025). "The results showed that EIF4EBP1, FOXM1, PLG, and VWF were highly expressed in renal carcinoma compared with normal renal tissue, and ADAM8, CGN, G6PC, ITIH4, and MMP3 were low in expression in renal carcinoma compared with normal renal tissue." (PMID 33968297, 2021).
sarcoma (3 papers, 2002 to 2022). A usually aggressive malignant neoplasm of the soft tissue or bone. "According to previous sarcoma studies, conversion of plasminogen to plasmin was observed on the sarcoma cell surface." (PMID 36258189, 2022). "The zymography of crude whole cell protein extracts (7 μg/total protein per sample) from solid DS-sarcomas exhibited two plasminogen-dependent proteolytic bands, one with strong, another with weak proteolytic activity in the 50 kDa region." (PMID 11953898, 2002).
schizophrenia (3 papers, 2018 to 2021). A major psychotic disorder characterized by abnormalities in the perception or expression of reality. "The role of C4BP in the activation of plasminogen, due to the association of the plasminogen activation system with schizophrenia, merits biochemical investigation of the synergistic impact of this crosstalk interaction on systemic complement and coagulation activity." (PMID 34226666, 2021). "Consistent with our findings, there is also an emerging literature implicating the plasminogen pathway in schizophrenia." (PMID 29875399, 2018).
serous ovarian cancer (3 papers, 2019 to 2021). "Our findings support these observations and suggest that ATRA acts predominately on S100A10 in the plasminogen activation pathway in serous ovarian cancer cells." (PMID 30621740, 2019). "Moreover, plasminogen (plg) was proved to be a favorable biomarker for prediction of survival in advanced high-grade serous ovarian cancer." (PMID 31718609, 2019).
streptococcal infection (3 papers, 2008 to 2020). Any of the several infectious disorders caused by members of streptococcus, a genus of gram positive bacteria belonging to the family Streptococcaceae. "As previously demonstrated for streptococcal infection, AF-induced plasminogen activation could trigger plasminogen-mediated destruction of extracellular matrix components, which in turn enhances tissue invasiveness of the pathogen." (PMID 18566672, 2008). "The only hypothesis about the origin of anti-CD26 autoantibodies in healthy controls links again CD26/DPP4 with plasminogen as a consequence of an abnormal immune stimulation triggered by streptokinase (SK) released during streptococcal infections, a mechanism that also produces antiplasminogen." (PMID 32051696, 2020).
thrombotic disorders (3 papers, 2013 to 2024). "Testing for thrombotic disorders revealed a protein S level of 10% (normal range: 77–143 for males), while plasminogen (PLG), antithrombin III (AT-III), and protein C tests were negative." (PMID 39465133, 2024). "Double uPA-tPA KO mice show extensive thrombotic disorders similar to those in plasminogen KO mice." (PMID 24120085, 2013). "Overall, we did not observe an association between PLG p.Arg172Gly and risk of thrombotic disease." (PMID 28787443, 2017).
abscess (2 papers, 2021 to 2025). An inflammatory process characterized by the accumulation of pus within a newly formed tissue cavity which is the result of a bacterial, fungal, or parasitic infection or the presence of a foreign body. "We have shown before that opening and draining of abscesses due to plasminogen activation by staphylokinase expressed in S. aureus decreased severity of skin infections." (PMID 33785850, 2021).
acute promyelocytic leukemia (2 papers, 2020 to 2021). An aggressive form of acute myeloid leukemia (AML), characterized by arrest of leukocyte differentiation at the promyelocyte stage, due to a specific chromosomal translocation t(15;17) in myeloid cells. "Both mechanisms, secondary and primary, of DIC, such as high levels of urokinase-type plasminogen activator (u-PA), annexin-II, tissue-type plasminogen activator (tPA), reduced the levels of plasminogen and α2-antiplasmin, and were present in APL (acute promyelocytic leukemia)." (PMID 35011859, 2021).